CRBN (cereblon)
Diseases named in the same sentence as CRBN in open-access papers (continued):
Sharing a sentence is not in itself a finding about the gene and the disease.
myeloma (continued). "After 2–6 months of Len treatment, drug resistance frequently develops as a result of down-regulation of CRBN mRNA and protein levels, which also indicates that CRBN protein levels regulate the sensitivity of myeloma cells to IMiDs." (PMID 33392195, 2020). "CRBN is known to be the binding target of thalidomide and lenalidomide, both immunomodulatory drugs used for the treatment of multiple myeloma." (PMID 32117034, 2020). "Although CRBN knockdown initially induces myeloma cell cytotoxicity, CRBN protein level is decreased in IMiD-resistant myeloma cells." (PMID 30683842, 2019). "CRBN mediates immunomodulatory drug (IMiD)-induced death of multiple myeloma cells by promoting the ubiquitination-mediated degradation of two transcription factors IKZF1 and IKZF326,27." (PMID 30683842, 2019). "The immunomodulatory imide drug (IMiD) lenalidomide promotes myeloma cell death via Cereblon (CRBN)-dependent ubiquitylation and proteasome-dependent degradation of IKZF1 and IKZF3." (PMID 30760870, 2019). "Another example is variants in CRBN (cereblon) and IRF4 that are involved in myeloma risk and additionally affect therapy responses." (PMID 31139207, 2019). "The backbone myeloma drug lenalidomide (Len) down regulates IRF4 indirectly because it lies downstream of cereblon (CRBN), the primary target of Len, in the CRBN-IKFZ1/3-IRF4-MYC pathway." (PMID 31139207, 2019). "In particular, CRBN knockout on myeloma cell lines leads to lenalidomide and pomalidomide resistance." (PMID 29780393, 2018). "It has also been reported that that majority of myeloma cell lines from patients resistant to thalidomide and other immunomodulatory drugs have very low levels of CRBN." (PMID 29746508, 2018). "In this study, we investigated the regulation of CRBN expression in human myeloma cell lines with both intrinsic and acquired resistance to IMiDs." (PMID 29130642, 2018). "It was gradually discovered that the antitumor effect of IMiDs on multiple myeloma and other hematologic diseases is mediated by CRBN either through a ubiquitin-dependent or a ubiquitin-independent pathway." (PMID 28894755, 2017). "CRBN knockdown in multiple myeloma cells showed significantly reduced CRBN expression and decreased cell viability." (PMID 28894755, 2017). "We have found that CRBN expression is required for the anti-myeloma activity of IMiDs and introduction of wild-type or His-tagged CRBN into IMiD-resistant cells increased their sensitivities to IMiD." (PMID 28926977, 2017). "One gene, cereblon, a myeloma treatment target, is found in strong linkage with the chromosome 2 region." (PMID 27575253, 2016). "A recent in vitro study conducted in our laboratory found that curcumin enhances the cytotoxic effects of lenalidomide in human multiple myeloma cells via suppression of the cereblon gene." (PMID 26199769, 2015). "Since stable CRBN depletion is cytotoxic for myeloma cells, these experiments were performed using transient infections." (PMID 26269456, 2015). "It was shown that not only thalidomide but also lenalidomide and pomalidomide bind to CRBN, attenuating the proliferation of myeloma cells through several pathways such as the down-regulation of autoubiquitination of CRBN." (PMID 25617756, 2015). "The absence and downregulation of CRBN expression in human myeloma cell lines result in IMiDs resistance, which is also supported by downregulation of CRBN expression at the time of lenalidomide resistance in MM patients." (PMID 24687382, 2014). "Cereblon (CRBN) is essential for the anti-myeloma (MM) activity of immunomodulatory drugs (IMiDs), such as thalidomide and lenalidomide." (PMID 24687382, 2014).
myeloma (continued). "Clinically validated examples include thalidomide analogs that recruit cereblon (CRBN) to degrade IKAROS family zinc finger 1/3 in multiple myeloma, and arylsulfonamide-based MGDs that promote the degradation of RNA-binding protein 39 in acute myeloid leukemia and solid tumors." (PMID 42220438, 2026). "Lastly, as new targeted agents emerge (e.g. cereblon E3 ligase modulators in myeloma and chimeric antigen receptor NK-cell therapies, etc.), it will be important to systematically monitor for ocular AEs from the outset, learning from the lessons of prior therapies." (PMID 41568391, 2025). "Epigenetic inactivation of CRBN has been observed in patients with refractory multiple myeloma." (PMID 38165043, 2024). "Additionally, CRBN overexpression enhanced lenalidomide’s anti-myeloma activity in the presence of LG100754." (PMID 37566072, 2023). "To confirm whether RXR agonists synergistically enhance the anti-myeloma activity of lenalidomide through altering CRBN expression, we genetically overexpressed CRBN in the MM cell lines." (PMID 37566072, 2023). "These molecules exert multiple direct and indirect anti-myeloma effects, primarily through binding to cereblon (CRBN), part of an E3 ubiquitin ligase complex, and promoting the ubiquitination of the IKAROS and AIOLOS family transcription factors (IKZF1 and IKZF3)." (PMID 37627065, 2023). "Myeloma patients with LEN resistance demonstrated a reduction in CRBN expression levels." (PMID 36765919, 2023). "In addition, IMiDs also directly affect myeloma cell survival by binding to Cereblon (CRBN) – a component of the CRL4CRBN E3 ubiquitin ligase complex (CUL4–ROC1–DDB1–CRBN)." (PMID 37744361, 2023). "Recent studies have identified Cereblon (CRBN) as a primary target of IMiDs anti-myeloma activity." (PMID 37799465, 2023). "Given the fundamental role of CRBN in the anti‐myeloma activity of IMiDs, it is reasonable to speculate that its dysfunction underlies cell insensitivity and resistance to IMiDs." (PMID 37581569, 2023). "Lastly, CELMoDs, which are an evolving treatment strategy for myeloma, build upon the long-standing success of IMiDs by using a slightly different molecular structure that allows for more enhanced interaction with traditional IMiD substrates such as cereblon." (PMID 36826140, 2023). "Nonetheless, bortezomib could potentiate the anti-myeloma effect of lenalidomide, suggesting that bortezomib may regulate the CRBN–lenalidomide–IKZF1/3 signaling pathway." (PMID 35321428, 2022). "Recently, we discovered that the proteasome inhibitors bortezomib and MG-132 could induce CRBN cleavage, which possibly attenuates the anti-myeloma effect of lenalidomide." (PMID 35321428, 2022). "CRBN is a lenalidomide-binding protein that mediates the anti-myeloma effect of lenalidomide." (PMID 35321428, 2022). "This study aimed to evaluate expression of CRBN in bone marrow plasma cells and investigate whether CRBN is related to the prognosis of multiple myeloma." (PMID 34336672, 2021). "This nomogram could improve the prognostic evaluation of the efficiency of IMiD therapy in myeloma patients with high CRBN expression and might provide personalized initial treatment strategies to clinicians." (PMID 34336672, 2021). "Aa a result, myeloma cell lines and primary tumors may become refractory to CRBN-dependent ubiquitylation and degradation induced by IMiDs." (PMID 35071234, 2021). "This nomogram could improve the prognostic evaluation of myeloma patients exhibiting high CRBN expression treated with IMiD therapy and might help provide personalized treatment strategies to clinicians." (PMID 34336672, 2021). "Several studies evaluated the prognostic value of CRBN in patients with multiple myeloma." (PMID 34336672, 2021). "In conclusion, the present study showed that IMiD therapy might have a clinical benefit in multiple myeloma patients exhibiting high CRBN expression." (PMID 34336672, 2021).
myeloma (continued). "A study reporting the effect of lenalidomide treatment on multiple myeloma patients indicated that PFS is significantly shorter in patients exhibiting low CRBN levels than in those exhibiting high CRBN levels (5.6 vs. 19.7 months) and a similar effect was observed for OS (11.4 vs. 30.5 months)." (PMID 34336672, 2021). "Indeed, truncation and point mutations in CRBN and DDB1 were discovered in myeloma cells and patient samples despite the fact that these mutations were rare." (PMID 33392195, 2020). "It has been demonstrated that high CRBN protein levels enhance the anti-myeloma activity of Len." (PMID 33392195, 2020). "On the one hand, CRBN is required for the anti-myeloma activity of Len." (PMID 33392195, 2020). "Cereblon (CRBN) is expressed in several malignant cell lines, such as myeloma and lymphoma cells." (PMID 31506802, 2020). "The CRBN-targeting immunomodulatory drug lenalidomide effectively promotes the degradation of many CRBN-binding substrate proteins, and is widely applied for the treatment of multiple myeloma." (PMID 32466489, 2020). "Using myeloma as a model system, we further demonstrated that blockage of the CRBN cleavage by pharmacological inhibition or genetic depletion of CASP-8 potentiates the anti-myeloma activity of Len in both myeloma cell lines and bone marrow primary myeloma cells." (PMID 33392195, 2020). "CRBN is a key modulator in the treatment of myeloma cells with Len and its structural analogs." (PMID 33392195, 2020). "The aim of this study was to evaluate the influence of selected clinical and molecular factors including single nucleotide polymorphisms (SNPs) in CRBN gene on the efficacy of first line CTD (cyclophosphamide, thalidomide, dexamethasone) chemotherapy in patients with multiple myeloma." (PMID 29844872, 2018). "Although cereblon is essential for lenalidomide-mediated direct tumoricidal activity against myeloma, it also mediated T cell activation by lenalidomide or its analogues because knockdown of cereblon in primary human T cells abrogates drug-induced IL-2 expression." (PMID 26447613, 2015). "In this study, by using the IHC scores consisted of both diffuseness and intensity of CRBN expression within myeloma cells, the semi-quantified results could be obtained." (PMID 24687382, 2014). "However, the requirement for high-quality clinical samples, such as myeloma cells enrichment by cell sorting, limits the validation of such quantified transcriptional expression of the CRBN gene method to every MM patient." (PMID 24687382, 2014). "Several clinical studies have correlated the higher expression of CRBN gene in myeloma cells with the superior treatment response of a lenalidomide-based regimen and a pomalidomide-based regimen, as well as longer progression-free survival during thalidomide maintenance therapy." (PMID 24687382, 2014). "However, further examination of CRBN status on additional human myeloma cell lines (HMCLs) and MM patients suggested that copy number abnormalities affecting the CRBN gene were rare events in MM." (PMID 24687382, 2014). "Among the 67 NDMM patients, the myeloma cells of 39 (58 %) patients were CRBN+." (PMID 24687382, 2014). "In the LD cohort, the myeloma cells of 19 (48 %) of the 40 patients were CRBN+." (PMID 24687382, 2014). "IMiDs not only target myeloma cells but also exert an indirect effect by activating the proliferation of the cytotoxic T and NK cells.The mechanism of IMiDs action was clearly described in studies, elucidating that cereblon (CRBN) plays an important role in mediating IMiDs anti-tumor effects." (PMID 36387095, 2022). "The impact of the cellular redistribution on CRBN activity was supported by the recruitment of this protein in aggresomes and its cytoprotective role in cells exposed to proteasome inhibitors as well as the requirement of nuclear import of CRBN for pomalidomide‐mediated anti‐myeloma activity." (PMID 34392531, 2021).
myeloma (continued). "Further studies reveal that CRBN also directly binds lenalidomide and pomalidomide, and depletion of CRBN blunts the inhibitory effect of lenalidomide and pomalidomide on proliferation of myeloma cells, indicating that CRBN is required for IMiD-mediated anti-proliferation and anti-myeloma activity." (PMID 34680233, 2021). "IMiDs may not be effective against residual myeloma cells with reduced CRBN burden and CBRN gene mutations." (PMID 34638353, 2021). "Thus, CRBN expression might have IMiD efficiency predictive value in multiple myeloma patients, although there is controversy regarding the appropriate method for measuring CRBN expression." (PMID 34336672, 2021). "Therefore, prediction strategies for high CRBN expression might help identify patients who might benefit from IMiD therapy and could improve the clinical outcomes of multiple myeloma patients." (PMID 34336672, 2021). "The result showed that those with lower CASP-8 mRNA levels exhibited a higher overall survival rate, suggesting that CASP-8 expression may be an important factor in determining the clinical response to Len-based therapies likely through the regulation of CRBN protein level in myeloma." (PMID 33392195, 2020). "Interestingly, CASP-8 activation by TRAIL and Btz also leads to CRBN cleavage in myeloma cells." (PMID 33392195, 2020). "Therefore, we thought to use myeloma cells as a model system to explore whether CASP-8 regulates CRBN levels after addition of Len." (PMID 33392195, 2020). "But based on the roles of IKZF1 and CRBN for eliciting anti-myeloma effects for any possible hematological response accompanying reduction in the disease burden (M-protein), it remains unclear if recovery of erythroid progenitors is CRBN or IKZF1 independent." (PMID 33014791, 2020). "Therefore, whether CRBN genetic variations can be prognostic markers of myeloma cell biology or predictive biomarkers of clinical response to IMiD-based therapy remain to be determined." (PMID 31619706, 2019). "Emerging evidence suggests that IMiDs can block MEIS2 from binding to CRBN facilitating the subsequent activation of a CRL4CRBNIMiD-E3-ubiquitin ligase activity and proteasome-mediated degradation of critical substrates regulators of Multiple Myeloma (MM) cell survival and proliferation." (PMID 30975979, 2019). "IMiDs bind to CRBN and redirect its E3 ubiquitin ligase activity to degrade key transcription factors (e.g., IKZF1/3), leading to myeloma cell death." (PMID 40650115, 2025). "In MM, Len binds to CRBN and promotes the ubiquitination and subsequent degradation of two lymphoid transcription factors, IKZF1 and IKZF3, which are essential for myeloma cell survival." (PMID 41463377, 2025). "To further validate the role of CRBN in lenalidomide and RXR agonist-mediated anti-myeloma effects, we used CRISPR/Cas9 technology to knock out the expression of CRBN in the U266 and MM1.R cell lines." (PMID 37566072, 2023). "Our previous study demonstrated that peroxisome proliferator-activated receptor (PPAR) agonists downregulated cereblon (CRBN) expression and reduced the anti-myeloma activity of lenalidomide in vitro and in vivo." (PMID 36358696, 2022). "Among these drugs, iberdomide (CC-220) is a novel compound with the highest reported specificity for CRBN and the lowest IC50, currently in a phase 2 clinical trial for systemic lupus erythematosus (SLE) and multiple myeloma (MM)." (PMID 35640596, 2022). "Lenalidomide recruits the neo-substrate IKZF1/3 onto CRBN and promotes ubiquitination and subsequent degradation by the CRL4CRBN E3 ligase, thereby exhibiting an anti-myeloma effect." (PMID 35321428, 2022). "In multiple myeloma cells, CBIs raise the levels of the NK-activating ligands MICA and PVR through cereblon-dependent degradation of IKZF-1/3 and IRF4." (PMID 33411730, 2021).
myeloma (continued). "In combination with CASP-8 inhibitor, Len further elevates the CRBN protein level, resulting in the enhanced degradation of IKZF1 and IKZF3 and enhanced anti-myeloma activity." (PMID 33392195, 2020). "Recent studies showed that IMiDs bind to CRBN, a substrate receptor of CRL4 E3 ligase, to induce the ubiquitination and degradation of IKZF1 and IKZF3 in multiple myeloma cells, contributing to their anti-myeloma activity." (PMID 31938543, 2020). "We further knocked down CRBN in RPMI8226 cells with lentivirus and treated the cells with z-IETD-fmk to investigate the anti-myeloma activity of Len." (PMID 33392195, 2020). "IMiDs bind to CRBN and recruit IKZF1 and IKZF3 for their ubiquitination and degradation, leading to the reduced proliferation of myeloma cells." (PMID 33392195, 2020). "For example, cytoplasmic anchorage of CRBN, and the resulting sequestration from Ikaros and Aiolos may attenuate their degradation in response to lenalidomide or pomalidomide, thereby providing a mechanism by which multiple myeloma cells can acquire resistance to these drugs." (PMID 32132601, 2020). "Upon binding to cereblon, IMiDs induce CRBN-dependent proteasomal degradation and inhibition of IKZF1/3, B cell-specific transcription factors required for both myeloma cell viability and activation of the immune system." (PMID 31619706, 2019). "This phenomenon is notable as IMiDs, which are commonly used as a front-line treatment for myeloma, target IKZF1 for CRBN-mediated ubiquitination and proteasomal degradation." (PMID 31015454, 2019). "In the HMCL that expresses the most abundant CRBN (JJN3), co-treatment with lenalidomide and SGC-CBP30 induced a significantly synergistic anti-myeloma activity." (PMID 30741931, 2019). "Previously, it has been shown that IMiDs antiproliferative activity in myeloma and CLL was dependent on CRBN." (PMID 29780393, 2018). "IMiDs directly bind Cereblon (CRBN), and promote substrates Ikaros and Aiolos to the CRL4Cereblon E3 complex for degradation, which is toxic to myeloma cells." (PMID 26460955, 2015). "Therefore, it is interesting to determine whether the expression of CRBN in myeloma cells is also regulated by ROS signaling, and whether the activation of the Nrf2 pathway can upregulate CRBN expression in CRBN− myeloma cells to recapture the sensitivity of IMiDs." (PMID 24687382, 2014). "Expanding our focus to other CRBN-high cancers, RNA-seq data from cancer cell lines in the Human Protein Atlas (HPA) identified AML as having the highest CRBN expression among cancer cell lines, followed by myeloma." (PMID 40551250, 2025). "The anti-myeloma potential of Dp44mT was found to be independent of CRBN expression or IMiD sensitivity." (PMID 41442907, 2025). "Recently, PI and IMiD combination treatment was shown to work synergistically via calpain-dependent IKZF1 cleavage and stabilization of CRBN levels, suggesting that PI plus POM treatment might be a promising alternative for LEN-refractory myeloma." (PMID 38004369, 2023). "Furthermore, in the progression free survival (PFS) analysis, newly diagnosed multiple myeloma (NDMM) individuals who underwent IMiD-based treatment regimen, and in whom a hypermethylation of CRBN enhancer was detected, had an inferior PFS." (PMID 36765919, 2023). "We have previously shown that PPARs agonists (fenofibrate, GW501516, and troglitazone) reduce the anti-myeloma effect of lenalidomide by downregulating the transcription activity of CRBN, while PPARs antagonists (GW3787, GW9662, and GW6471) increase CRBN expression and improve lenalidomide activity." (PMID 36358696, 2022). "IMiD binding to CRBN resulted in proteasomal depletion of the IKAROS family members IKZF1 (Ikaros) and IKZF3 (Aiolos) that are the lymphoid transcription factors crucial in myeloma cell survival." (PMID 36499765, 2022). "Consistently, CRISPR/Cas9-mediated knockout of CRBN in myeloma cell lines did not alter expression levels of these proteins." (PMID 35197447, 2022).